SEMA3A (semaphorin 3A)
Diseases named in the same sentence as SEMA3A in open-access papers (continued):
Sharing a sentence is not in itself a finding about the gene and the disease.
atopic dermatitis (6 papers, 2018 to 2022). "Decreased expression/production of sema3A in the skin of atopic dermatitis as well as in psoriatic patients was found to be associated with itch and disease severity." (PMID 29670620, 2018). "In various disorders, such as atopic dermatitis (AD), epidermal Sema3a may be strongly associated with IENFD." (PMID 32566683, 2020). "Repeated application of Sema3A ointment significantly inhibited scratching behavior and improved dermatitis scores in mice, thus improving the pathophysiology of atopic dermatitis (AD)." (PMID 35347234, 2022). "Sema3A plays a regulatory role in experimental mouse models as well as in human models of allergic rhinitis, atopic dermatitis and asthma." (PMID 30967873, 2019). "Topically applied Sema3A ointment inhibits scratching behavior and improves skin inflammation in NC/Nga mice with atopic dermatitis." (PMID 29849491, 2018). "sema3A replacement was reported to normalize the hyper-innervation in atopic dermatitis, resulting in suppression of itching suggesting sema3A to be a potential therapeutic strategy in a wide spectrum of immune-mediated inflammatory diseases." (PMID 29670620, 2018). "Sema3A might also modulate epidermal innervation in atopic dermatitis." (PMID 35347234, 2022). "Sema3A together with NGF acts as axon-guidance molecules in the skin in inflammatory skin disorders, such as atopic dermatitis." (PMID 36012289, 2022).
lung carcinoma (6 papers, 2018 to 2024). "For example, miR‐362 was shown to interact with SEMA3A and silence its expression to promote lung cancer." (PMID 39177014, 2024). "The results also showed that the expression levels of PLAUR and SEMA3A were significantly upregulated in the lung cancer tissues." (PMID 36091160, 2022). "Additionally, although sema3A usually functions as a tumor suppressor, it was discovered that plexin-A1 can mediate sema3A oncogenic signals in lung cancer cells." (PMID 37627074, 2023). "IHC staining also confirmed that HNRNPAB, PLAUR, and SEMA3A protein expressions in lung cancer specimens were significantly increased, which supported our hypothesis." (PMID 36091160, 2022). "In addition, we found plant-derived traditional Chinese medicine components targeting both HNRNPAB and SEMA3A, including 17 beta-estradiol, a natural compound exhibiting broad anti-cancer effects against lung cancer." (PMID 36091160, 2022). "In mouse models of pancreatic neuroendocrine tumors and cervical carcinoma, the expression of Sema3A overcomes proinvasive and prometastatic resistance, while the knockdown of Sema3A increased the sensitivity of Lewis lung cancer cells to EGFR-TKIs gefitinib and erlotinib." (PMID 33921219, 2021). "Gastric, ovarian, or lung cancer, exhibit a negative correlation between SEMA3A expression and cancer progression." (PMID 38263416, 2024).
non-small cell lung carcinoma (6 papers, 2014 to 2022). A group of at least three distinct histological types of lung cancer, including non-small cell squamous cell carcinoma, adenocarcinoma, and large cell carcinoma. "Moreover, we identified some diseases and phenotypes related to HNRNPAB/PLAUR/SEMA3A from the database, including non-small cell lung carcinoma (NSCLC), colorectal carcinoma (CRC) and LUAD (disorder)." (PMID 36091160, 2022). "In addition, miR-362-5p directly binds and negatively regulates the expression of Semaphorin 3A (Sema3A) in non-small cell lung cancer (NSCLC) to enhance the cell invasion and migration in vitro and tumor formation in vivo." (PMID 32194406, 2020). "Downregulated SEMA3A expression was also observed in non-small cell lung cancer (NSCLC)." (PMID 28611294, 2017). "In the present study, the correlation between the expression levels of semaphorin-3A and MMP-14, and their subsequent prognostic significance in non-small cell lung cancer (NSCLC), was investigated." (PMID 24765144, 2014).
osteosarcoma (6 papers, 2018 to 2022). A usually aggressive malignant bone-forming mesenchymal neoplasm, predominantly affecting adolescents and young adults. "Although these findings indicate that Sema3A may have a potential role in protecting the skeleton from osteosarcoma-associated osteolysis, our in vivo studies were restricted to the human KHOS model of immuno-deficient mice." (PMID 29720701, 2018). "Furthermore, our present results - when combined with published work - suggest that Sema3A has overlapping roles in regulating osteolysis, but it exerts differential effects on osteoblast differentiation and osteosarcoma associated ectopic bone formation." (PMID 29720701, 2018). "Together, these findings have led us to hypothesize that Sema3A plays a role in the regulation of osteosarcoma associated bone remodelling." (PMID 29720701, 2018). "Although the signaling mechanisms by which Sema3A affects bone cell differentiation and function are yet to be fully characterised, we present evidence to suggest that DKK1/β-catenin signalling may be one mechanism by which Sema3A influences osteosarcoma-associated ectopic bone formation." (PMID 29720701, 2018). "In view of the fact that Sema3A is highly expressed in and secreted by cells of osteoblastic origin, and previous findings that implicated Nrp1 and Nrp2 receptors in osteosarcoma, we examined the role of Sema3A in osteolysis and abnormal bone formation associated with osteosarcoma." (PMID 29720701, 2018). "As a result, it is possible that restraint of RANKL by denosumab induces aberrant osteoblasts differentiation and osteosarcoma tumorigenesis via Sema3A." (PMID 33123484, 2020). "Third, RANKL expression upregulates semaphorin 3A gene expression in osteosarcoma cell lines, and knockout of this gene stimulates deregulated bone and cartilage growth." (PMID 30868006, 2018). "Exposure of the osteoblast-like cell MC3T3 and the more differentiated osteosarcoma cells MG-63 and Saos-2 to exogenous Sema3A (300 ng/ml) enhanced alkaline phosphatase activity (p < 0.001, p < 0.01 and p < 0.05 respectively), without affecting cell viability." (PMID 29720701, 2018). "Together, these results implicate the autocrine DKK1/GSK3β/β-catenin signaling in the regulation of osteoblast differentiation by osteosarcoma-derived Sema3A." (PMID 29720701, 2018). "Since Sema3A is known to selectively bind to its co-receptor Nrp1, further studies were conducted to determine if the anti-migratory effects of osteosarcoma derived Sema3A in our models were truly mediated by Nrp1." (PMID 29720701, 2018). "Our interpretation of these differences is that exogenous Sema3A and overexpression of Sema3A in KHOS cells exerts differential effects on the ability of osteosarcoma cells to enhance bone formation." (PMID 29720701, 2018). "Human recombinant (exogenous) Sema3A promoted the expression of osteoblastic phenotype in a panel of human osteosarcoma cell lines and inhibited the ability of these cells to migrate and enhance osteoclastogenesis in vitro." (PMID 29720701, 2018). "Previous studies have shown that Sema3A is secreted by osteoblasts, and its co-receptors Nrp1 and 2 have been detected in human osteosarcoma cells." (PMID 29720701, 2018). "Previous studies have shown that primary osteoblasts express Sema3A, and osteosarcoma cells express its co-receptor Nrp1 and 229,31,34." (PMID 29720701, 2018). "Nonetheless, mice inoculated with human KHOS osteosarcoma cells overexpressing Sema3A exhibited a trend towards more bone volume indicative of a modest osteoprotective effect." (PMID 29720701, 2018). "With this in mind, we tested the effect of human recombinant Sema3A (exogenous) on the ability of various human osteosarcoma cell lines to grow, migrate, express osteoblast features and influence osteoclast formation in vitro." (PMID 29720701, 2018).
osteosarcoma (continued). "In conclusion, Sema3A plays a role in the osteoanabolic and metastatic properties of osteosarcoma cells and it inhibits osteosarcoma cell ability to stimulate osteoclastogenesis." (PMID 29720701, 2018). "Here, we find that mice injected with human KHOS osteosarcoma cells overexpressing Sema3A had reduced osteoclast numbers (Oc.N/BS) and suppressed osteoclast activity (Oc.S/BS)." (PMID 29720701, 2018). "Consequently, RANKL inhibition by denosumab possibly leads to the abnormal differentiation of osteoblasts and osteosarcoma tumorigenesis through Semaphorin 3A." (PMID 35735433, 2022). "Lastly, RANKL upregulates the Semaphorin 3A gene level in osteosarcoma, and its deletion could induce the bizarre growth of cartilage and bone." (PMID 35735433, 2022). "SEMA3A can inhibit the ability of osteosarcoma cells to stimulate osteoclast production." (PMID 33203792, 2020). "Thirdly, RANKL upregulates the level of Sema3A gene in osteosarcoma, and deletion of this gene could lead to aberrant cartilage and bone growth." (PMID 33123484, 2020). "Here, we report a previously unknown role of Sema3A in the regulation of ectopic bone formation and osteolysis related to osteosarcoma." (PMID 29720701, 2018). "Interestingly, Sema3A expression was reduced in the metastatic osteosarcoma cells MNNG/HOS, POS-1, MOS-J and K7M2 when compared to the osteoblast-like cells Saos-2." (PMID 29720701, 2018). "We have consistently showed that Sema3A reduced the motility of a panel of osteosarcoma cell lines including KHOS, consistent with the anti-migratory action of osteosarcoma-derived Sema3A and the action of Sema3A previously reported in both neuronal and cancer cells." (PMID 29720701, 2018). "These in vitro results suggest that treatment with Sema3A may be beneficial to reduce osteosarcoma growth and metastasis in vivo." (PMID 29720701, 2018). "Together, these results imply that tumour-derived Sema3A reduces the ability of osteosarcoma cells to cause ectopic bone formation without affecting their growth." (PMID 29720701, 2018). "Therefore, further studies will be required to determine if Sema3A is effective in reducing the development and progression of osteosarcoma in other models." (PMID 29720701, 2018). "Here, we show that a panel of human and murine osteosarcoma cell lines express and secrete Sema3A." (PMID 29720701, 2018). "Thus, the inhibition of RANKL expression by denosumab therapy is expected to induce abnormal proliferation and differentiation of osteoblasts and bring about semaphorin 3A-mediated osteosarcoma carcinogenesis." (PMID 30868006, 2018). "Moreover, Sema3A enhances bone volume in mice inoculated with human osteosarcoma cells." (PMID 29720701, 2018). "In support of this hypothesis, we show that the human recombinant Sema3A reduced the ability of human osteosarcoma cells to influence bone activity and its administration in mice enhanced bone volume in the absence and presence of KHOS cells in the bone microenvironment." (PMID 29720701, 2018). "Thus, Sema3A is of potential therapeutic efficacy in osteosarcoma." (PMID 29720701, 2018). "A surprising finding of the present study was that osteosarcoma-derived Sema3A inhibited the formation of new ectopic bone in mice inoculated with KHOS cells, contrasting with the osteoanabolic effects of Sema3A in mice reported in previous studies." (PMID 29720701, 2018). "Exposure to exogenous Sema3A (300 ng/ml) reduced the directed migration of the osteoblast-like cell MC3T3 and the human osteosarcoma cell lines MG-63, MNNG/HOS (p < 0.01), KHOS and Saos-2 (p < 0.05)." (PMID 29720701, 2018). "Previous studies have shown that Sema3A enhances osteoblast differentiation but its effects on the metastatic and osteolytic behaviour of the osteoblast-like osteosarcoma cells have not been investigated." (PMID 29720701, 2018).
Sepsis (6 papers, 2015 to 2025). Sepsis is defined as life-threatening organ dysfunction caused by a dysregulated host response to infection. "In our sepsis cohort, SEMA kinetics were linked to sepsis complications with SEMA3A, SEMA3C, SEMA4D and SEMA7A associated with mortality." (PMID 40869413, 2025). "In conclusion, we have shown that patients with sepsis have different serum concentrations of SEMA3A, SEMA3C, SEMA3F, SEMA4D, and SEMA7A compared to healthy controls and that their kinetics during sepsis correlate with disease severity and outcomes." (PMID 39770766, 2024). "Blocking SEMA3A in sepsis led to a decreased secretion of TNF-α and IL-6, which was associated with lower mice mortality." (PMID 39770766, 2024). "Mouse models of sepsis by means of intraperitoneal injection of LPS reveal the role of SEMA3A, SEMA3E and their receptors PLXNA4 and PLXND1, respectively, in propagating the inflammatory cascade." (PMID 34012455, 2021). "On the contrary, NRP1, which has been identified as a co-receptor for SEMA3A, is shown to down-regulate the systemic inflammatory response of sepsis." (PMID 34012455, 2021). "This is the case with miR-223, which plays a protective role in both autoimmune hepatitis (by regulating NLRP3 and caspase-1) and in sepsis (by inhibiting Sema3A and Stat3)." (PMID 31533317, 2019). "During polymicrobial sepsis, miR-223 contained inside EVs contributes to the regulation of two proteins, semaphorin-3A (Sema3A) and signal transducer and activator of transcription 3 (Stat3), which are involved in apoptosis." (PMID 28224125, 2017). "As a result, the miR-223 targets (i.e., Sema3A and Stat3) were down-regulated, leading to the inhibition of inflammatory response in macrophages and attenuation of cardiomyocyte death during sepsis." (PMID 26348153, 2015). "Sema3A and Stat3 are considered fundamental activators of the sepsis process." (PMID 31533317, 2019). "Patients with sepsis had significantly higher serum levels of SEMA3C, SEMA3F, SEMA4D, and SEMA7A and a significantly lower SEMA3A." (PMID 39770766, 2024). "While SEMA3A was decreased, SEMA3C, SEMA3F, SEMA4D, and SEMA7A were increased in sepsis patients." (PMID 39770766, 2024). "While SEMA3A was decreased, SEMA3C, SEMA3F, SEMA4D, and SEMA7A were increased in sepsis patients, and all analyzed SEMA showed good accuracy in identifying patients with sepsis." (PMID 39770766, 2024). "On the contrary, exosomes released from miR-223-absent MSCs contain higher levels of Sema3A and Stat3, which might be delivered to macrophages and cardiomyocytes, leading to promotion of macrophage inflammation and cardiomyocyte death in sepsis." (PMID 26348153, 2015).
type 2 diabetes (6 papers, 2019 to 2025). "Further, the dysregulated Sema3a signaling is relevant to the type 2 diabetes-associated peripheral neuropathy." (PMID 32566683, 2020). "Our results demonstrate that HFD dysregulates the A2AR-mediated Sema3a expression, with functional implications for the type 2 diabetes-induced peripheral neuropathy." (PMID 32566683, 2020).
Arrhythmia (5 papers, 2009 to 2022). Any cardiac rhythm other than the normal sinus rhythm. "Cardiac innervation patterning is disrupted in Sema3a-deficient and Sema3a-overexpressing mice, leading to sudden death or lethal arrhythmias." (PMID 21037846, 2009). "In conclusion, Sema3a-CreERT2 is the first genetic mouse tool for the specific targeting of Purkinje fibres and provides a means for the in vivo functional study of Purkinje fibres during ventricular conduction system formation and cardiac arrhythmias." (PMID 29403069, 2018). "However, it is believed that arrhythmias in Brugada syndrome are exacerbated by vagal stimulation, which might suggest SEMA3A as a candidate gene for future studies of Brugada syndrome." (PMID 23593042, 2013).
endometriosis (5 papers, 2015 to 2024). The growth of functional endometrial tissue in anatomic sites outside the uterine body. "On the other hand, hypoxia-induced Semaphorin 3A (Sema3A), a local secreted protein with axono-repulsive action, has also been involved in Mφ recruitment in endometriosis." (PMID 34639133, 2021). "Recently, Sema3A has been detected in peritoneal and deep infiltrating endometriosis, and it is proved to play a potential role in mediating the aberrant sympathetic innervation in the lesion." (PMID 28288663, 2017). "This indicates that SEMA3A, as a nerve-repellent factor, may be responsible for the altered sympathetic innervation of endometriosis." (PMID 38541683, 2024). "In addition, another study showed that Sema3A can recruit Mφ through the Sema3A/Nrp-1 (Neuropilin-1) signaling pathway, guiding them to a hypoxic environment like endometriosis lesions." (PMID 34639133, 2021). "Thus, it is reasonable to speculate that Sema3A may be a potential medium to regulate the progress of macrophage migration and the following interaction with nerve fibers in the lesion of endometriosis." (PMID 28288663, 2017). "Interestingly, SEMA3A and SEMA3C expression is markedly increased in women with endometriosis." (PMID 38541683, 2024). "Additionally, Sema3A is an axon-repulsive guidance factor for neurons, and Sema3A/NRP-1 signaling recruits macrophages to the hypoxic microenvironment, such as the peritoneal cavity of endometriosis, and polarize macrophages from the M1 phenotype toward the M2 phenotype." (PMID 36865552, 2023).
lupus nephritis (5 papers, 2012 to 2023). Glomerulonephritis in the context of systemic lupus erythematosus. "The expression of Sema3A and its receptor, neuropilin-1, was decreased in peripheral blood of mononuclear cells (PBMC) in patients with SLE, while the expression of Sema3A was strong in the tubules in lupus glomerulonephritis." (PMID 36012289, 2022). "The expression of sema3A was also assessed in the glomeruli and tubuli of suffering from lupus nephritis and found to be in inverse correlation with renal function assays." (PMID 29670620, 2018). "We demonstrated the high beneficial effect of sema3A in ameliorating lupus nephritis in NZB mice by delaying the appearance and deterioration of proteinuria and increasing the survival rate." (PMID 29670620, 2018). "In a previous study of ours, we assessed the possible involvement of sema3A, sema4A and sema4D in contributing to or regulating glomerular inflammation in lupus nephritis." (PMID 25978359, 2015). "Of note, an analysis of SEMA3A immunostaining in kidneys from patients with lupus nephritis (LN) revealed an increase in SEMA3A expression in patients with LN, while SEMA3A expression was negatively associated with clinical–pathological parameters, including proteinuria and kidney function." (PMID 37835781, 2023). "Further studies will establish the idea of applying sema3A in the treatment of lupus nephritis." (PMID 29670620, 2018). "In addition, the association between the sema3A serum levels and the presence of lupus nephritis was evaluated: 73% of patients with a sema3A level below 50 ng/ml had kidney involvement." (PMID 22697500, 2012).
lymph node metastasis (5 papers, 2012 to 2022). "According to a univariate analysis, SEMA3A expression, lymph-node metastasis, pathological stage and T-stage were associated with overall survival in this patient population (P = 0.001, P = 0.018, P = 0.013 and P = 0.034, respectively." (PMID 26755661, 2016). "It was suggested that lower levels of SEMA3A may promote pleural and vascular invasion and lymph-node metastasis." (PMID 28611294, 2017). "The present study demonstrated that both the expression of semaphorin-3A and MMP-14 in the observation group were closely associated with pleural invasion, lymph node metastasis, the number of metastatic lymph nodes, the degree of differentiation, vascular invasion and expression of PNCA." (PMID 24765144, 2014). "Significantly lower expression of SEMA3A was observed in the lymph node metastasis group." (PMID 22926477, 2012). "In our study, we also found that SEMA3A expression inversely correlated with lymph node metastasis." (PMID 22926477, 2012). "In the NSCLC group, the positive rates of semaphorin-3A and MMP-14 expression were relevant to pleural invasion, lymph node metastasis, the number of metastatic lymph nodes, the degree of differentiation, vascular invasion and PCNA expression." (PMID 24765144, 2014).